BRD4 (bromodomain containing 4)
Diseases named in the same sentence as BRD4 in open-access papers (continued):
Sharing a sentence is not in itself a finding about the gene and the disease.
cancer (continued). "The transcriptional co-factor BRD4 facilitates the recruitment of Mediator (a multiprotein complex involved in the transcriptional regulation by RNA polymerase II) to active enhancers, thus leading to important roles in pluripotency and cancer." (PMID 36358822, 2022). "The effects of MALAT1 suppression and BET inhibitor JQ1 on the malignant phenotypes and cancer stem cell- (CSC-) like properties of laryngocarcinoma cells as well as the expression of bromodomain-containing protein 4 (BRD4), YAP1, and EMT markers were investigated." (PMID 35601153, 2022). "We found that 44.1% of the 12,339 BRD4-enriched enhancers had at least 1-base pair overlap with active enhancers in normal tissues and this number increases to 73.6% when compared to active enhancers across several cancer types." (PMID 35869079, 2022). "The BRD4 gene is recognized as a promising target for cancer therapy." (PMID 35204785, 2022). "In addition, we found a significant positive correlation between KEAP1 and BRD4 at the mRNA level in most cancer types." (PMID 35453346, 2022). "Similar to TRIM28, the exact mechanism of BRD4‐associated cancer stemness‐high phenotype is not clear, although unequivocally it depends on bromodomain activity." (PMID 35049055, 2022). "First, GEPIA2 data found high levels of BRD4 expression in a subset of cancers, including GBM." (PMID 36224471, 2022). "Inhibition of Brd4 reduces cancer cell viability in vitro and suppresses tumor growth in vivo, by inducing cell apoptosis, autophagy, pyroptosis or ferroptosis in different contexts, indicating a critical role of Brd4 in the regulation of program cell death (PCD)." (PMID 36539410, 2022). "Moreover, several reports have shown that BRD4 promotes cancer cell proliferation and that inhibition of BRD4 leads to cancer cell death." (PMID 36158208, 2022). "Brd4 inhibition has been demonstrated to induce apoptosis in many different types of cancer cells." (PMID 36539410, 2022). "Colorectal cancer (CRC) is one of the types of cancer in which the BRD4 protein is overexpressed." (PMID 36232374, 2022). "In this study, we explored the expression of BRD4 across different cancer cell lines and found that BRD4 was highly expressed in AML cell lines, indicating the dependence of AML cell lines on BRD4 for survival and the usage of BRD4 as a potential therapeutic target." (PMID 35832114, 2022). "BRD4, an epigenetic reader, is one of the most important BET proteins and plays an important role in angiogenesis and the development of inflammation-associated and cardiovascular diseases, central nervous system disorders and cancers." (PMID 35563588, 2022). "Although the mechanisms regulating p-BRD4 levels may vary by cancer type, targeting this critical event may provide a feasible treatment for these cancers." (PMID 35402244, 2022). "Therefore, BET inhibition has been effective in preclinical studies of multiple cancer types, especially for many hematopoietic system cancers that rely on constant BRD4 activity to express MYC." (PMID 35303910, 2022). "As an important component of SEs, BRD4 combines with RNA-Pol II and p-TEFb in the transcription of oncogenes, keeping cancer cells in a relatively immature stem cell like state and driving the occurrence and development of cancer to a certain extent." (PMID 35303940, 2022). "As BRD4 is frequently upregulated in various cancers and plays multiple oncogenic roles, including promotion of cell proliferation and metastasis, selective inhibitors of BRD4 are key molecules that are investigated using preclinical and clinical models of solid tumors." (PMID 36139416, 2022). "Therefore, early attention to the relationship between BRD4 and ferroptosis will help clinics design meaningful ferroptosis interventions in advanced cancers." (PMID 36309482, 2022). "Efficacy of the bromodomain 4 (BRD4) inhibitor JQ1 has been reported for the treatment of various human cancers, but its potential impact on EC remains unclear." (PMID 35902869, 2022).
cancer (continued). "Aberrant BRD4 expression may contribute to the progression of multiple cancers, including hematological malignancies and several types of solid cancers." (PMID 35902869, 2022). "In this regard, targeting the phase separation ability of BRD4 may be a novel strategy for treating cancer." (PMID 35159127, 2022). "Moreover, we identified nucleoporinNUP210 as an NUP upregulated in a BRD4-dependent manner, which contributes to cancer cell growth and maintenance of the nuclear architecture in CRC." (PMID 35159127, 2022). "Epigenetic factor Brd4 has emerged as a key regulator of cancer cell proliferation." (PMID 36539410, 2022). "Despite showing lower potency than previouslyreported JQ1-based degrader MZ1, the RNF4-based PROTAC 19 (entry 19)could degrade BRD4 in a time and dose-responsive manner in 231MFPbreast cancer cells." (PMID 36110375, 2022). "However, studies have shown that SPOP mutations in endometrial cancer promote the accelerated degradation and reduction of BRD4 protein, thus making cancer cells sensitive to BETis." (PMID 35402244, 2022). "Brd4 is overexpressed in many cancer cells and assumed to be a negative regulator of apoptosis." (PMID 36539410, 2022). "Targeted inhibition of Brd4 suppresses growth and induces apoptosis of various cancer cells." (PMID 36539410, 2022). "Dysregulation of BRD4 is frequently observed in various human cancers." (PMID 36475791, 2022). "Furthermore, BRD4 inhibition induces the immunogenic cell death of cancer cells and subsequently induces phagocytosis by dendritic cells and expansion of CD8+ cytotoxic T cells." (PMID 36139513, 2022). "In addition to cancer treatment, Brd4 inhibitors have been studied in animal models for the treatment of inflammatory diseases, such as sepsis, multiple sclerosis and liver fibrosis that have been reported to be necroptosis-related diseases." (PMID 36539410, 2022). "Given that BRD4 is frequently elevated in cancer cells compared to normal cells, co-targeting of BRD4 and the KEAP1-Nrf2-G6PD axis might not only maximize the clinical efficacy of BET inhibitors but also cause fewer side effects in patients." (PMID 35453346, 2022). "BRD4 physically associated with YAP/TAZ transcription factors, increasing expression of a number of different growth-regulating genes that are essential for the progression of cancer cells." (PMID 35831279, 2022). "However, most previous studies of BETi mainly examined BRD2/BRD3/BRD4 proteins in cancer cells; few studies have considered the effects of BETi on macrophages." (PMID 35094142, 2022). "Therefore, combination of PARP and BRD4 inhibitors can induce synthetic lethality in HR-proficient cancers." (PMID 35328658, 2022). "JQ1 is one of the first compounds capable of inhibiting, with nanomolar potency, the binding of BRD4 with DNA, consequently preventing the development of cancer cells (to which it activated the process of apoptosis, being, currently, a therapeutic weapon in acute leukemia)." (PMID 36232374, 2022). "In addition to BRD-NUT-driven malignancies, the BRD4 gene was found to be amplified across 20 types of common cancers." (PMID 34681760, 2021). "Recent studies indicate that genomically instable cancer phenotype in patients with BRD4 amplification could be attributed to less efficient DNA repair mechanisms." (PMID 34758842, 2021). "Although the critical role of Myc in regulating glucose metabolism in tumor and T cells is well-studied and Brd4 inhibitors are broadly applied in HIV-1 latency reversal and cancer therapy, it is unclear whether Brd4 inhibition affects CD8+ T-cell responses." (PMID 34512660, 2021). "Finally, we demonstrate that bivalent inhibitors induce a conformational change within BRD4 dimers in vitro and in cancer cells." (PMID 34754068, 2021). "Consistent with our results, Brd4 was also detected at human promoters following BD inhibition or mutation, which explains why BET degradation outperforms BET inhibition in preclinical cancer models." (PMID 34137374, 2021).
cancer (continued). "Members of the BET protein family (BRD2, BRD3, BRD4, and BRDT) are implicated in various cancers." (PMID 32647323, 2021). "In addition, since BRD4 has been shown to enhance the escape of cancer cells from immunosurveillance through the regulation of the programmed death 1 (PD-1)/PD-L1 immune checkpoint, inhibition of BRD4 holds the potential to elicit an antitumor immune response." (PMID 33958721, 2021). "In addition, newly emerging data revealed that BRD4 isoforms exhibit contradicting functions in cancer." (PMID 34758842, 2021). "IGF1R and INSR genes are direct targets of BRD4 in several cancer models." (PMID 34440844, 2021). "Moreover, the cross-talk between PAKs and other oncogenic/pathogenic signaling pathways, such as CDKs/PAKs, EGFR/PAKs, and BRD4/PAKs, is very important in cancer progression and drug resistance." (PMID 33796531, 2021). "In addition, H3K27, H3K9 acetylation and BRD4 recruitment were shown to alter the chromatin status and promoted transcription of PD-L1 in cancer cells." (PMID 34365463, 2021). "Thus, CDK9 and BRD4 have emerged as druggable targets for the development of cancer therapies, through suppression of constitutive expression of anti-apoptotic proteins." (PMID 34146121, 2021). "One such BET protein, bromodomain-containing protein 4 (BRD4), is a target in multiple cancers." (PMID 34862404, 2021). "Moreover, inhibitors for bromodomain-containing 4 (BRD4), one reader of H3K27ac on enhancer, were shown to be effective in cancer treatment." (PMID 34737287, 2021). "Therefore, BRD4 has become a promising anti-cancer drug target that attracts huge interest in discovering BRD4 inhibitors." (PMID 33820450, 2021). "BET (bromodomain and extra terminal domain) containing proteins including BRD2, BRD3 and BRD4 are chromatin remodeling epigenetic proteins that target acetylation-dependent histone modifications and hence play important roles in cancer progression, invasion and metastasis 7,8." (PMID 34803511, 2021). "In the contrast, BRD4 mRNA expression was significantly elevated in cancer tissues." (PMID 33686960, 2021). "Inhibiting BRD4 displays efficacy against diseases especially cancer and inflammation." (PMID 33820450, 2021). "BET proteins, specifically BRD4, have demonstrated potential as drug targets in lung and other cancers leading to the initiation of a myriad of clinical trials; however, mechanisms of response and resistance to these inhibitors are still poorly understood, especially across different cancer types." (PMID 33712563, 2021). "Furthermore, inhibition of BRD4 is synthetically lethal with PARPi in multiple mouse models of cancer, including HR-proficient pancreatic cancer." (PMID 34572943, 2021). "Inhibition of BRD4 function has an effective anti-cancer effect, reducing tumor growth whether ablated by single agents or in combination with other drugs." (PMID 34758842, 2021). "Furthermore, inactivation of BRD4 activity or downregulation of BRD4 expression by inhibitors is used in cancer therapy target to repress these cell cycle-related genes." (PMID 34336926, 2021). "BRD4 has been shown to maintain constitutively active NF-kB in cancer cells." (PMID 34400879, 2021). "BRD4 plays an oncogenic role and is a potential target of therapy in various cancers." (PMID 35372800, 2021). "In addition to interacting with acetylated histones, BRD4 also promotes cancer progression by regulating the interaction with transcription factors in cancer cells." (PMID 33850096, 2021). "Therefore, the deubiquitinases involved in the regulation of BRD4 stability appear to be cancer-dependent." (PMID 34290255, 2021). "The authors concluded that BRD4 isoforms have opposing functions in TNBC and that post-transcriptional regulation may play a critical role influencing BRD4 protein isoform abundance during cancer progression." (PMID 34758842, 2021).
cancer (continued). "Unlike PD-L1 negative regulators (HDAC1, HDAC2, and HDAC3), the expression ranks of PD-L1 and its positive regulators (EP300, CREBBP, IRF-1, and BRD4) negatively correlated to Grade Group in another study, suggesting an increase of function during cancer progression." (PMID 34830196, 2021). "BRD4 has thus emerged as a critical therapeutic target for a wide variety of cancers." (PMID 32575711, 2020). "BRD4 has also been reported to promote metastasis in cancer cells." (PMID 32303673, 2020). "Brd4 was first shown to control the cell cycle and cell identity determination, with this protein being regarded as an essential regulator for maintaining cancer progression and metastasis and a promising target for anticancer treatment." (PMID 32982695, 2020). "However, many of the affected cancers have also acquired BETi resistance, highlighting the limitations of BETi therapy and the complex nature of BRD4′s regulation." (PMID 32575711, 2020). "However, the cellular pathways that regulate BRD4 function and the mechanistic role of BRD4 alternation in cancer remain largely unexplored." (PMID 32575711, 2020). "The importance of BRD4 in tumorigenesis has been demonstrated by its ability to bind to acetylated histones and regulate transcription of oncogenic genes involved in several types of cancers." (PMID 31908141, 2020). "Dysregulation of BRD4 contributes to the pathogenesis of a wide range of cancers." (PMID 32575711, 2020). "Recent evidence suggests that BRD4 could also contribute to the pathogenesis by regulating the transcription of genes relevant to cancer stem cells such as ALDH1A1, LIF, HES1, and WNT5A." (PMID 33488950, 2020). "We therefore examined whether inhibition of only one bromodomain of BRD4 could lead to sufficient anti-cancer effects." (PMID 32694708, 2020). "Previous studies have demonstrated that BRD4 inhibition or depletion could induce apoptosis activation in human cancer cells." (PMID 32371868, 2020). "The abnormal activity of the BET protein, which recognizes lysine residues of both histones and non-histones, especially BRD4, is closely associated with cancer progression, making BET a promising therapeutic target." (PMID 33109235, 2020). "For instance, Brd4, a well-studied member of the BET family, is known to activate genes involved in cell growth and cell cycle progression which are some of the prominent features associated with cancer cells." (PMID 32224969, 2020). "Moreover, CDK9 participates to MYC gene transcription in a number of cancer types through the recruitment of P-TEFb to chromatin by the bromodomain-containing protein 4, BRD4, which recognizes the acetylated histone tails." (PMID 32903585, 2020). "Our finding suggests that CDK1 over-activation in cancers could also contribute to BETi resistance by stimulating BRD4 hyperphosphorylation and downstream target gene expression." (PMID 32575711, 2020). "In addition, both CDK1 upregulation and BRD4 hyperphosphorylation have been observed in BETi-resistant cancer cells." (PMID 32575711, 2020). "It was shown that BRD4 is highly enriched in super-enhancers that drive the expression of factors that are critical for the pathogenesis of cancer such as c-MYC, suggesting that targeting BET family proteins could be a promising approach for cancer treatment." (PMID 32286255, 2020). "BRD4 inhibitors are used as promising chemotherapeutic drugs for cancer therapy." (PMID 32208449, 2020). "Furthermore, BRD4 has been reported to regulate the expression of tumor-related inflammatory cytokines and promote the development and progression of cancer." (PMID 32303673, 2020). "Moreover, BRD4 is important for the activation of oncogenic nuclear factor-kappa B signaling in cancer cells." (PMID 32371868, 2020). "We also provide experimental evidence to support that blocking BRD4 hyperphosphorylation with CDK1 inhibitors could be employed to overcome BETi resistance in cancer." (PMID 32575711, 2020).
cancer (continued). "However, BRD4 inhibition results in feedback elevation of BRD4 protein in human cancer cells, leading to weak anti-proliferative activity and less apoptosis induction." (PMID 32978368, 2020). "BRD4 has thus emerged as a key anti-cancer therapeutic target." (PMID 32575711, 2020). "In other malignancies, BRD4 associates with cancer-specific super enhancers, hematopoietic transcription factors in acute myeloid leukemia, YAP/TAZ, and other pro-tumorigenic transcription factors to promote proliferation and cancer progression." (PMID 32151278, 2020). "Moreover, JQ1 disrupted the interactions between BRD4 and NF-κB, and blocked the activation of NF-κB signaling in cancer cells." (PMID 32303673, 2020). "To clarify whether BRD4 is associated with OSCC, as in many other cancers, we performed qRT-PCR and examined the BRD4 expression levels in tissues from biopsy specimens of OSCC patients." (PMID 32499570, 2020). "We identified Brd4 as one of the critical molecules that regulate Il34 expression in cancer cells." (PMID 33072227, 2020). "Moreover, recent reports suggesting that BRD4-mediated regulation of EMT-TFs is required for the invasion and metastasis of cancer cells further rationalize the future use of BRD4 as a promising therapeutic target for aggressive tumors." (PMID 32824207, 2020). "Previous studies have reported that BRD4 is involved in the development of cancer and inflammation." (PMID 32303673, 2020). "Moreover, BRD4 is largely acknowledged for its roles in organization of super-enhancers and oncogene expression in cancer." (PMID 32208449, 2020). "We suggest another beneficial effect of BRD4 inhibitors in cancer immunotherapy." (PMID 32208449, 2020). "BRD4 has been reported to be a drug target for several cancers." (PMID 33344510, 2020). "The BRD4 inhibitor (+)-JQ1 (JQ1) has been shown to suppress the proliferation of cancer cells by inducing apoptosis, indicating that JQ1 may be a new therapeutic agent for cancer treatment." (PMID 32103754, 2020). "Indeed, inhibition of BRD4 by inhibitors revealed the involvement of BRD4 in various cancers in animal models." (PMID 33344510, 2020). "It has been shown that BRD4 inhibitors could have reversible binding and incomplete inhibition of BRD4, which largely compromise the anti-cancer cell activity." (PMID 32163373, 2020). "In addition, PD-L1 is downstream of BRD4, and BRD4 inhibition facilitates the anti-tumor immune response in cancer patients by suppressing PD-L1 expression." (PMID 33658927, 2020). "Our efforts have led to the discovery of a representative compound 13 (4-chloro-2-methoxy-N-(2-oxo-2H-chromen-6-yl)benzenesulfonamide), which binds to BRD4 with nanomolar affinities and shows low micromolar potencies in cell growth inhibition against four human cancer cell lines." (PMID 30879350, 2019). "Indeed, the targeted BRD4 inhibitor JQ1 has been used in cancer therapy and has exhibited promising therapeutic results in cancer." (PMID 30988278, 2019). "Wnt5a is a non-canonical Wnt ligand which is overexpressed specifically in BLBC cell lines, and the inhibition of the Twist-bromodomain containing 4 (BRD4) association by JQ1 reduced Wnt5a expression and suppressed invasion, cancer stem cell (CSC)-like property, and tumorigenicity of BLBC cells." (PMID 31462314, 2019). "BRD4 is an important regulator of gene activity in several cancers." (PMID 31085420, 2019). "It has been documented that various transcriptional factors, such as STAT3, MYC, p65 and BRD4, could directly bind to the promoter of PD-L1 and regulate the transcription of PD-L1 in cancer cells." (PMID 30709380, 2019). "However, dual targeting of BRD2 and BRD4 have presented some limitations, recent studies revealed their opposing biological effects in some cancer types, which BRD2 inhibition increased cancer cell invasiveness." (PMID 31523195, 2019).